RNU2-30P (RNA, U2 small nuclear 30, pseudogene)
Gene: Small nuclear RNA gene on chromosome 1 (52,754,322 to 52,754,462, forward strand). Ensembl gene ENSG00000252018.
Homologues: Orthologues: mouse Gm25475 (38% identical), macaque U2 (38% identical), rabbit U2 (36% identical), rat LOC120094028 (35% identical). Paralogues in human: RNU2-2 (65% identical), RNU2-59P (65% identical), U2 (65% identical), RNU2-4P (64% identical), RNU2-3P (62% identical), RNU2-6P (62% identical), RNU2-20P (61% identical), RNU2-23P (61% identical), RNU2-36P (61% identical), RNU2-43P (61% identical), RNU2-8P (60% identical), RNU2-17P (60% identical), and 66 more.